CD4 (CD4 molecule)
Diseases named in the same sentence as CD4 in open-access papers (continued):
Sharing a sentence is not in itself a finding about the gene and the disease.
myocardial infarction (continued). "Studies reported that patients with myocardial infarction have lower CD4+ but higher CD8+ T lymphocytes." (PMID 30534069, 2018). "Collectively, the results shown here indicate that CD4+Foxp3+ Tregs act in a paracrine manner to promote CM proliferation during development, in both the maternal and the embryonic heart, and after myocardial infarction." (PMID 29946151, 2018). "CD4+ T lymphocytes can differentiate into Th1 and Th2 lineage in response to the local milieu of cytokines during myocardial infarction." (PMID 30534069, 2018). "Liuzzo and colleagues reported the presence of CD4+CD28null T cells in patients with unstable angina or myocardial infarction." (PMID 28084533, 2017). "Myocardial infarction induces activation and proliferation of CD4+ T cells in a cardiac antigen-specific manner, as mice with CD4+ T cells specific to an irrelevant antigen fail to mount a response." (PMID 29163503, 2017). "In patients with unstable angina and myocardial infarction, the expansion of an unusual subset of CD4+ T cells has been described." (PMID 28084533, 2017). "When CD4 + CD25+ T cells were investigated in the setting of acute myocardial infarction, the inhibitory activity of CD4 + CD25+ regulatory T cells was found to be modified with atorvastatin treatment." (PMID 26822994, 2016). "Seven days after myocardial infarction the mouse hearts clearly demonstrated the presence of CD4+CD25hi lymphocytes." (PMID 25436994, 2014). "A recent study described a role for Tregs in a rat model of myocardial infarction, and in a study in mice it was shown that CD4+ T-cells become activated after myocardial infarction and facilitate wound healing of the myocardium." (PMID 25436994, 2014). "We have recently demonstrated that myocardial infarction rapidly induces activation of proliferation of CD4+CD25+Foxp3+ T-cells in heart draining lymph nodes." (PMID 23740214, 2013). "Transfer of CD4+CD25+ T-cells was further reported to attenuate myocardial remodeling after experimental myocardial infarction in mice." (PMID 23740214, 2013). "Patients with acute myocardial infarction had significant shorter mTL in their CD4+ T cells 24 h after PPCI (2.9±0.9 vs. 3.5±0.8 kB, p = 0.01) when compared to healthy age-matched controls." (PMID 23077561, 2012). "Understanding the interplay between the innate immune system and CD4+ T helper cells, along with their cytokines, is crucial for developing targeted therapies to mitigate myocardial infarction and reperfusion injury, ultimately improving outcomes for cardiac patients." (PMID 38879568, 2024). "In addition, injection of myocardial infarction-induced splenic CD4(+) AT2R(+) T cells into recipient rats with myocardial infarction has been shown to reduce infarct size and improve cardiac function." (PMID 39917605, 2024). "Different subsets of CD4+ Th cells (such as Th1, Th2, Th9, Th17, and Th22) secrete various cytokines and play distinct roles in inflammation, anti-inflammation, and remodeling/repair following myocardial infarction and reperfusion." (PMID 38879568, 2024). "CD4+ T lymphocytes seem to exhibit biphasic kinetics post-myocardial infarction whereby CD4+ T cells facilitate wound healing in the acute phase of myocardial infarction but their further recruitment in the heart from the 10th day to 8 weeks after STEMI promotes left-ventricular dysfunction." (PMID 37426649, 2023). "Cumulative CD4 counts were used as a predictor of acute myocardial infarction and mortality compared to VACS index, viremia-years, and time-updated single measurements of viral load and CD4, and was found associated with acute myocardial infarction to the lowest CD4 count level." (PMID 35602655, 2022). "The CD4+ and CD8+ T cells in plaques are in an activated state that promotes the formation of atherosclerotic lesions and the development of plaques to vulnerable plaques, possible causing myocardial infarction or ischemic stroke on rupturing." (PMID 36110551, 2022).
myocardial infarction (continued). "Moreover, specific ablation of CD4 T cells reduces the initial healing and remodelling response after myocardial infarction and aortic constriction through the formation of mature collagen matrix and fibrosis." (PMID 35723764, 2022). "Importantly, IL‐7 was detected in intestinal I/R in vitro and in vivo 38 and was identified as an expansion and activation driver of CD4 + CD28null T cells in myocardial infarction patients." (PMID 34581005, 2021). "However, the way in which different CD4+ T subtypes function in the myocardial infarction/reperfusion (MI/R) heart is still poorly understood." (PMID 31011288, 2019). "CD4/CD28-null T cells accumulate preferentially in unstable ruptured coronary plaques and have been suggested to promote plaque instability and predispose ACS patients to recurrent acute coronary events (myocardial infarction) and indicate a poor prognosis." (PMID 31565659, 2019). "Therefore, miR-142-3p targeting the downregulation of exosomes derived from CD4+ T cell activation may be a promising basis for the treatment of adverse cardiac remodeling after myocardial infarction." (PMID 39350967, 2024). "CD4+ T-cells facilitate wound healing post-myocardial infarction (MI) but promote left-ventricular (LV) remodeling during ischemic heart failure (HF; 8 weeks post-MI)." (PMID 36093172, 2022). "On the other hand, activated CD4+ T-cells are indispensable for suitable collagen scar deposition, which avoids left ventricular rupture and dilation after myocardial infarction (MI)." (PMID 31011288, 2019). "Therefore, we postulate that although plaque size is comparable between patients and controls, the increase in CD4+CD28null T cells in AAV patients may result in an increased propensity for myocardial infarction." (PMID 28084533, 2017). "Further studies confirmed the deleterious effects of cardiac infiltrating T cells (including CD4+ and CD8+ subpopulations) on the cardiac lymphatic system after myocardial infarction." (PMID 40463382, 2025). "In human hearts, B cells are present at similar levels to CD4+ and CD8+ T cells; however, in the mice model, during acute myocardial infarction, a temporary decrease in circulating B cells is observed, followed by an increase 24 h after reperfusion." (PMID 39940640, 2025). "TGR5 activation in CD4 T cells inhibits inflammation by regulating the recruitment of CD4 and CD8 T cells after myocardial infarction." (PMID 37111068, 2023). "Using a murine myocardial infarction (MI) model, the authors found that the administration of activated CD4+ T cell-derived sEV elicited a deterioration of cardiac function post-MI, which was dependent on miR-142-3p, a miRNA enriched in the plasma of heart transplant patients." (PMID 37762077, 2023). "This includes ischemic heart diseases like myocardial infarction where pro-inflammatory macrophages release pro-inflammatory cytokines and other immune cells, like T cells, for example, CD8 + and CD4 + T cells are involved." (PMID 35312907, 2022). "We showed previously that stimulation of CD4+ Foxp3+ regulatory T-cells by superagonistic anti-CD28 monoclonal antibodies (mAb) improves myocardial healing after experimental myocardial infarction (MI)." (PMID 32298302, 2020). "In our lymphocyte analysis, the CD4+/CD8+ double positive cells and NK cells were also significantly decreased after myocardial infarction." (PMID 31865532, 2020). "Lymphocyte subsets analysis in peripheral blood revealed significant alterations in CD4+/CD8+ ratio and naïve and effector/memory T cell percentages at 1 h post-myocardial infarction." (PMID 30898123, 2019). "CD4+CD25+Foxp3+ regulatory T cells (Treg cells) have protective effects in wound healing and adverse ventricular remodeling after myocardial infarction (MI)." (PMID 27144181, 2016). "We chose four different time points after myocardial infarction and measured the levels of CD4+CD25+FOXP3 out of the total splenic CD4 population." (PMID 25436994, 2014).
myocardial infarction (continued). "To investigate the pattern of CD4+ T cells following PPCI, we compared leukocyte subsets from 18 age-matched healthy controls to patients with acute myocardial infarction following PPCI (24 h, n = 31 and 6 months, n = 24)." (PMID 23077561, 2012). "In that direction, the roles of both CD4 and CD8 T cells as might occur in myocardial infarction or chronic heart failure and infections such as group B coxsackieviruses and Trypanosoma cruzi can be investigated in Tg mice." (PMID 37830560, 2023). "Through the endocrine mechanism, MI DEXs could mediate the activation of CD4+ T cells and improve cardiac function after myocardial infarction, which provides a basis for a new strategy of systemic delivery of DEXs for treating MI." (PMID 36465167, 2022). "Nevertheless, ablation of CD4+ T-cells alone does not offer the same protection in the adult heart after myocardial infarction, suggesting a developmental change of immune cells including CD4+ T-cells in the regulation of age-related mammalian heart repair." (PMID 32724455, 2020). "Not only CD4 + T cells and CD8+ T cells were altered after myocardial infarction." (PMID 31865532, 2020). "Research reported that Mice depleted of DCs could cause a severe inflammatory response and worse left ventricular remodeling after MI.I In addition, exosomes derived from DCs could migrate to lymphoid tissue and improve cardiac function after myocardial infarction via activation of CD4+ T cells." (PMID 40463382, 2025). "Moreover, mice without CD4+ T-cells retained a higher ejection fraction and microvascular reperfusion than wild-type mice in acute myocardial infarction/reperfusion (AMI/R) models." (PMID 31011288, 2019). "A study of myocardial infarction in mice found that the absence of CD4+ T-cells (which interact with MHC class II) in CD4 knock-outs, resulted in greater mortality and abnormal collagen formation compared to wild-type mice, with even greater mortality in mice that lacked all four MHC class II genes." (PMID 28132643, 2017).
vitiligo (73 papers, 2009 to 2025). Generalized well circumscribed patches of leukoderma that are generally distributed over symmetric body locations and is due to autoimmune destruction of melanocytes. "The expression level of this lncRNA in CD4+ T cells was meaningfully associated with the severity of vitiligo." (PMID 39881955, 2025). "In conclusion, this study showed that the expression of LOC100506314 was elevated in CD4+ T cells from patients with vitiligo and associated the severity of vitiligo." (PMID 37731844, 2023). "The expression levels of LOC100506314 in CD4+ T cells was positively and significantly associated with the severity of vitiligo." (PMID 37731844, 2023). "As expected, the expression of LOC100506314 was elevated CD4+ T cells from patients with vitiligo and associated the severity of vitiligo." (PMID 37731844, 2023). "In a murine model of vitiligo, CD4 T cells have been implicated as the main effector T cells." (PMID 28646041, 2017). "Specifically, LC and Mac‐TR demonstrated enhanced MHC‐I and CD4 signaling with CD4+ T cells, indicating alternatively enhanced antigen presentation in vitiligo skin." (PMID 41498037, 2025). "Initially, the flow cytometry analysis of PBMCs revealed a significant decrease in the CD4+/CD8+ T cell ratio in vitiligo mice compared to the normal group (1.04 ± 0.05 vs. 1.79 ± 0.17; p < 0.001)." (PMID 40725033, 2025). "The CD4+/CD8+ T cell ratio is decreased in progressive vitiligo, and successful repigmentation is accompanied by an elevated CD4+/CD8+ T cell ratio of the lesions." (PMID 40725033, 2025). "Studies that examined the function of CD-4 positive T-cells in both vitiligo and T1DM have addressed the connection between the two conditions, albeit a particular target shared by both disorders has not yet been identified." (PMID 39845243, 2024). "Highly significant changes in the levels of CD4+CD8α-, CD4-CD8α+ and CD4+CD8α+ T cells were detected over time in growing feathers of vitiligo-expressing Smyth chickens (P = 0.0003, < 0.0001 and < 0.0001, respectively)." (PMID 38720888, 2024). "Highly significant, positive correlations between the D-score of TCR-β2 and infiltrating αβ2 T (P < 0.0001), CD4-CD8α+ (P < 0.0001) and CD4+CD8α+ (P = 0.0003) cells were found in data obtained from vitiligo-expressing Smyth chickens." (PMID 38720888, 2024). "Meanwhile, we observed a significant increase in the number of CD4+Foxp3+ Tregs in the peripheral blood of vitiligo mice treated with 2D‐Exos and 3D‐Exos compared to the PBS group, higher in 3D‐Exos treatment group." (PMID 38887870, 2024). "Perilesional inflammatory infiltrate in vitiligo consists of both CD4 + & CD8 + cells, often with an increased CD8 + /CD4 + ratio." (PMID 36920542, 2023). "Using microarray analysis, we found that the expression levels of LOC100506314 increased in CD4+ T cells from patients with vitiligo and correlated with the severity of vitiligo." (PMID 37731844, 2023). "After adjusting for sex, age, and duration of disease, the severity of vitiligo measured by VES was positively, statistically significantly associated with the expression levels of LOC100506314 in CD4+ T cells (p=0.012)." (PMID 37731844, 2023). "Both CD4+ T lymphocyte and CD4+/CD8+ of vitiligo patients declined, compared with the normal control group (P<0.05)." (PMID 35035426, 2022). "It should be noted that this vitiligo model requires transient depletion of CD4 + T cells in the early stage of induction, which not only depletes Treg cells but also other CD4 + T cells, such as Th1 cells." (PMID 36182982, 2022). "Infiltrates of T lymphocytes, predominantly of the CD8+ phenotype, in addition to CD4+ T lymphocytes, were found in the lesions of patients with vitiligo, indicating an anti-melanocyte response mediated by CD8+ T lymphocytes." (PMID 35884944, 2022).
vitiligo (continued). "There were higher percentages of CXCR3(+) CD8(+) T cells in vitiligo patients compared with controls, while the expression of CXCR3(+) CD4(+) T cells also increased in patients with progressive vitiligo." (PMID 33679890, 2021). "Changes in CD4+ T cell functions and the presence of autoreactive melanocyte-specific cytotoxic T cells play important roles in vitiligo pathogenesis." (PMID 33968147, 2021). "Several blood endotyping studies have depicted that patients with vitiligo have low frequencies of circulating CD4+/CD8+ CLA+ TEM/TCM cells compared to patients with PSO, being similar to HC, supporting that CLA+ T cells migrate to the skin." (PMID 33833765, 2021). "Within T cell subsets, patients with vitiligo have the highest frequency of CD4+/CD8+ CLA+ T cells producing IFN-gamma compared with patients with AD, PSO, and alopecia areata (AA), and HC, supporting that vitiligo is caused by a type 1 T cell response." (PMID 33833765, 2021). "Consistent with the literature describing CD8+ T cell role in melanocytes death under IFN-gamma stimulation, CD8+ CLA+ T cell population producing IFN-gamma predominates over CD4+ CLA+ T cell subset in patients with vitiligo." (PMID 33833765, 2021). "Some studies have demonstrated that patients with VKH that have vitiligo have a predominance of CD4+ T-cell lymphocytes and an imbalanced ratio of CD4+/CD8+ T-cells, though others have demonstrated a CD8+ cytotoxic T cell preponderance." (PMID 33384688, 2020). "A histological analysis of vitiligo patients’ skin biopsy revealed that the margin zones of depigmented lesions were strongly dominated by CD4+ and CD8+ T cells." (PMID 32443482, 2020). "Some studies suggest that in lymphocytes Th CD4+, Th1 and Th17 are the major subset in vitiligo development." (PMID 32443482, 2020). "In classical vitiligo, increased CD8 + cytotoxic T-cell response, together with a decrease in CD4 + T-cells, causes melanocytes destruction." (PMID 32555205, 2020). "Nevertheless, the higher frequency of CD4+ T cells in SL feathers during vitiligo alone cannot explain the viral loads observed." (PMID 33092272, 2020). "Flow cytometric analysis revealed a significant decrease in the percentage of CD4+Foxp3+HO‐1+ T cells in vitiligo patients." (PMID 29974998, 2018). "Lymphocyte analysis to peripheral blood of patients with vitiligo showed the total levels of T-cells are normal, but the ratio of CD4+/CD8+ is decreased." (PMID 29456788, 2017). "Several reports including ours have suggested a decreased CD4+⁄CD8+ ratio in vitiligo patients, indicating the prevalence of CD8+ cells in patients." (PMID 28700671, 2017). "In our study, the percentage of CD4+CD25+ T cells in the peripheral blood of vitiligo patients was significantly lower than healthy controls." (PMID 26788051, 2015). ", while a statistically significant positive correlation was observed between peripheral percentage of FoxP3+ Tregs and the percentage of CD4+CD25+ cells in vitiligo patients (r = 0.369, P < 0.05)." (PMID 26788051, 2015). "In contrary, it was suggested that the reduced cell number and impaired function of natural Treg cells is associated with imbalance of CD4+/CD8+ ratio and was suggested to be involved in the T-cell mediated pathogenesis of vitiligo and its progression." (PMID 26257775, 2015). "Further, our results are supported by the cell based studies which showed an increased number of CD8+ T cells compared to CD4+ T cells in the blood samples of active vitiligo compared to the stable one." (PMID 26442157, 2015). "In the current study a negative correlation was observed between the percentage of peripheral CD4+CD25+ T cells in vitiligo patients and disease activity according to VIDA score." (PMID 26788051, 2015). "In another report, the percentage of CD4+CD25+ T cells was significantly elevated in the vitiligo patient cohort relative to normal control donors and this finding had been considered as a protective mechanism against the autoimmune process." (PMID 26788051, 2015).